GDAP2 (ganglioside induced differentiation associated protein 2)
Synonyms: FLJ20142; dJ776P7.1; MACROD3; SCAR27
Tractability: PROTAC: ubiquitination databases record sites on it; its protein half-life has been measured.
Gene: Protein-coding gene on chromosome 1 (117,863,485 to 117,929,662, reverse strand). Ensembl gene ENSG00000196505.
Subcellular location (Human Protein Atlas): Endoplasmic reticulum
Gene Ontology:
Molecular function: protein binding
Cellular component: lysosomal membrane
Genetic constraint (gnomAD): Loss-of-function variants: 4 observed, 5.73 expected, observed/expected ratio (o/e) 0.7, 90% interval 0.34 to 1.54. That is too few expected variants to judge how well the gene tolerates losing a copy. Missense variants: 63 observed, 69.29 expected, observed/expected ratio (o/e) 0.91, 90% interval 0.74 to 1.12. Synonymous variants: 22 observed, 23.7 expected, observed/expected ratio (o/e) 0.93, 90% interval 0.66 to 1.33.
Gene-disease validity (ClinGen):
ClinGen rates the evidence that GDAP2 causes each of these diseases.
spinocerebellar ataxia, autosomal recessive 27 (autosomal recessive): Strong. A form of spinocerebellar ataxia, a clinically and genetically heterogeneous group of cerebellar disorders due to degeneration of the cerebellum with variable involvement of the brainstem and spinal cord.
Homologues: Orthologues: chimpanzee GDAP2 (99% identical), macaque GDAP2 (99% identical), guinea pig GDAP2 (97% identical), dog GDAP2 (97% identical), rabbit GDAP2 (96% identical), pig GDAP2 (96% identical), mouse Gdap2 (95% identical), rat Gdap2 (93% identical), tropical clawed frog gdap2 (75% identical), zebrafish gdap2 (74% identical), Drosophila melanogaster Gdap2 (41% identical). Paralogues in human: MACROD2 (19% identical), MACROD1 (15% identical).
Diseases named in the same sentence as GDAP2 in open-access papers:
GDAP2 is named in the same sentence as 11 diseases in open-access papers, as found by Europe PMC text mining. Sharing a sentence is not in itself a finding about the gene and the disease. The quoted sentences say what the papers report.
Spinocerebellar ataxia (3 papers, 2023 to 2025). "Previous studies indicate that the downregulation of GDAP2, a member of the GDAP family, is associated with cerebellar ataxia in mammals." (PMID 40332832, 2025). "The variant detected in the GDAP2 gene is pathogenic according to ACMG classification and causes “Spinocerebellar ataxia, autosomal recessive 27” disease." (PMID 38587696, 2024).
asthma (1 paper, 2021). "Some mRNAs/lncRNAs were found as new risk factors associated with ABPA or asthma, i.e., AL139423.1-201, GDAP2, which might be novel biomarkers and targets for diagnosis and therapy in both diseases." (PMID 34221710, 2021).
Cerebellar atrophy (1 paper, 2024). Cerebellar atrophy is defined as a cerebellum with initially normal structures, in a posterior fossa with normal size, which displays enlarged fissures (interfolial spaces) in comparison to the foliae secondary to loss of tissue. "In addition, the variant detected in the GDAP2 gene was considered to be responsible for the patient’s phenotype like cerebellar atrophy in brain MRI." (PMID 38587696, 2024).
Cognitive impairment (1 paper, 2025). Abnormal cognition is characterized by deficits in thinking, reasoning, or remembering. "GDAP2 was significantly upregulated across diverse pathological hallmarks when comparing by degree of cognitive impairment." (PMID 39867396, 2025).
hereditary cerebellar ataxia (1 paper, 2025). Cerebellar ataxia that is transmitted from parent to child. "Ganglioside-induced differentiation-associated protein 2 (GDAP2) is a gene involved in hereditary cerebellar ataxia." (PMID 40332832, 2025).
GDAP2 also shares sentences with these, for which no sentence is quoted: autosomal recessive cerebellar ataxia (1 paper); cerebellar ataxia (1); dementia (1); lysosome disease (1); neurologic disease (1); spinocerebellar ataxia type 27 (1).